INS (insulin)
Diseases named in the same sentence as INS in open-access papers (continued):
Sharing a sentence is not in itself a finding about the gene and the disease.
Obesity (continued). "Several studies performed in humans and rodents reported that a chronic low-grade inflammation at the systemic level as well as within insulin-responding tissues (e. g. skeletal muscle and white adipose tissue) is the central mechanism leading to IR development in obesity." (PMID 27111539, 2016). "During obesity and pregnancy, a decrease in insulin sensitivity raises the body’s need for insulin." (PMID 28123396, 2016). "For example, in livers and adipose tissues of diet-induced obesity mice, overexpression of miR-103/107 negatively regulates insulin signaling by targeting Cav-1, a caveolae protein that activates insulin signaling by stabilizing the interaction between caveolae and IRS-1." (PMID 27763497, 2016). "However, further elucidation of the role of obesity, insulin signaling and the particular role of PTEN in cancer development is still required." (PMID 27893783, 2016). "A close relationship exists between obesity and insulin regulation." (PMID 27517904, 2016). "In addition to exercise, leptin replacement therapy, inhaled insulin therapy, and caloric restriction have also been proposed to improve obesity." (PMID 26881095, 2016). "Therefore, conditions which impair insulin signaling, such as obesity induced metabolic inflammation, also impair skeletal muscle glucose metabolism." (PMID 27128935, 2016). "Indeed, dendritic cells, mast cells, neutrophils, B cells and T cells have been found to reside in adipose tissue during obesity and contribute to the development of adipose tissue inflammation and insulin resistance." (PMID 26940592, 2016). "However, much work is still required to elucidate the interaction between nitrate and inflammation in obesity, including a focus on the effects of dietary nitrate on the expression of iNOS in insulin‐target tissues, such as skeletal muscle and adipose tissue." (PMID 26227946, 2016). "Of note, the identified associations between metabolites and obesity were independent of known obesity indicators including age, lifestyle, dietary energy intake and insulin resistance." (PMID 27434237, 2016). "In addition, parameters related to obesity, insulin sensitivity, hepatic steatosis, inflammation and gut barrier function were examined." (PMID 27125264, 2016). "Our results suggest that NEAT may be beneficial for the management of obesity, insulin sensitivity, and lipid profiles in patients with mental disorders." (PMID 26765475, 2016). "However, the information obtained from the mRNA profiles helped to understand why only the HFD+B29 mice developed obesity, got insulin-resistant phenotype, and aggravated inflammatory conditions." (PMID 27877172, 2016). "Insulin, a hormone related to lipid metabolism, contributes to the development of obesity." (PMID 27058520, 2016). "DM2 and obesity may promote PDAC through pro-tumorigenic insulin and insulin-like growth factor-1 (IGF-1) as well as chronic inflammation." (PMID 26641266, 2015). "Similarly, preservation of insulin sensitivity through PTP1B deletion or pharmacological inhibition of PTP1B protects against obesity-, hypertension- and heart failure- induced endothelial dysfunction." (PMID 25974252, 2015). "In addition, the reduced expression of NLRP3 in obesity results in enhanced insulin signaling, decreased inflammation, and improved insulin sensitivity." (PMID 26136779, 2015). "Given the large population of obesity and the discounted efficacy of chemotherapy in gastric cancer treatment of obese patients, to investigate whether insulin lead to resistance to 5-fluorouracil has significant clinical value." (PMID 26084465, 2015). "First, the prevention of obesity/lowering fat mass, particularly visceral fat, reductions in glucose and insulin levels improving insulin sensitivity, a reduction in oxidative stress and/or increase in antioxidant defense mechanisms, and a reduction in body temperature." (PMID 26061745, 2015).
Obesity (continued). "Using this method, we observed that the intestinal mucosa is insulin resistant in human obesity." (PMID 25631620, 2015). "Our objective was to test the hypothesis that reducing insulin secretion by partial disruption of the Ins2 gene would prevent diet-induced obesity." (PMID 26155745, 2015). "Innate pattern recognition receptors (PRRs) are increasingly recognized as direct or indirect sensors of excessive nutrients instigating a chronic inflammatory response in adipose tissue during obesity, with possibly detrimental effects on insulin sensitivity levels." (PMID 25867514, 2015). "HFD-fed mice given Gly-MCA had improved insulin sensitivity and resolution of fatty liver, and thus the question arises whether these improved metabolic endpoints are the result of lower obesity." (PMID 26670557, 2015). "Given the evolutionary conserved roles of insulin, it is possible that suppressing hyperinsulinaemia early in life may have far-reaching consequences on obesity in full-grown adult humans." (PMID 26155745, 2015). "To confirm that our finding of LHCGR overexpression is a PCOS-specific effect, we identified GEO datasets that could be analyzed with either obesity or insulin sensitivity as a dichotomous trait." (PMID 26305227, 2015). "Previous reports have found that the adult offspring of IUGR rats displayed hyperphagia, obesity, hypertension, high serum leptin and insulin levels, increased hypothalamic density of leptin and serotonin receptors, and impairment of serotonin and insulin hypothalamic signaling." (PMID 26633942, 2015). "Thus, apoC-III is induced in obesity by dysregulation of insulin and glucose signaling, and is intricately involved in establishing hypertriglyceridemia." (PMID 26633899, 2015). "Since obesity and diabetesmellitus can cause hyperfiltration,GFR was significantly higher in PCOS group inmultiple regression analysis including BMI, HOMA-IR, glucose, age, waist circumference, CRPand insulin." (PMID 26246875, 2015). "Leptin expression can be induced by obesity, insulin and TNF-α." (PMID 26379553, 2015). "In addition, ETS treatment markedly reduced body weight and adiposity, probably acting in part through anti-obesity, insulin sensitizing, and antioxidant mechanisms." (PMID 26512643, 2015). "It was observed that prevalence of obesity and resistance to insulin in women with PCOS is significantly higher when compared to the population in general making the LAP index a new, cheap and accessible predictor of the metabolic syndrome both to the general population and women with PCOS." (PMID 26104466, 2015). "This provided a unique model with which to test the hypothesis that the reduction of insulin secretion in young, growing mice can provide long-term protection against diet-induced obesity." (PMID 26155745, 2015). "Alternatively,” irisin resistance” may be another description for increased levels of irisin in obesity, as has already established for leptin or insulin in obesity." (PMID 27354972, 2015). "The changes in glucose and insulin levels may have subsequent effects on food intake or may promote weight gain and obesity." (PMID 25774705, 2015). "Specifically, we have reported that supplementation with both EGCG and BCAA suppresses obesity-related colorectal carcinogenesis in db/db mice by reducing serum levels of insulin and inhibiting activation of the IGF/IGF-1R signaling pathway in the colonic mucosa." (PMID 25789501, 2015). "Thus, C57BL/6J mice were successfully led to obesity with impaired insulin sensitivity by HFD for 22 weeks." (PMID 25747866, 2015). "Moreover, the discovery of new alternative pathways for the polarization of ATMs toward an M2 phenotype is necessary to better understand the mechanisms by which insulin sensitivity in obesity." (PMID 26779183, 2015).
Obesity (continued). "Indeed, microglia and astrocytes participate in the hypothalamic inflammatory response to high fat diet (HFD)-induced obesity, with this process contributing to inflammatory-related insulin and leptin resistance." (PMID 25859240, 2015). "Moreover, a study showed that elevated body iron stores have a detrimental effect on obesity-related conditions and that iron removal improves insulin sensitivity." (PMID 26358367, 2015). "Since several studies using animal models of diet-induced obesity have shown beneficial effect of resveratrol on improving insulin sensitivity and obesity, many clinical trials were performed to speculate its effect as an antidiabetic agent in humans." (PMID 26180596, 2015). "Further studies confirmed that ω-3 PUFA had an anti-obesity effect and enhanced insulin sensitivity and glucose homeostasis in rodent models of IR: the replacement of a small proportion of the diet with ω-3 PUFAs from fish oil completely prevents the development of skeletal muscle IR." (PMID 26834644, 2015). "The central insulin response is also attenuated by aging and diet-induced obesity." (PMID 26236282, 2015). "In addition to atherosclerosis, we examined a variety of metabolic traits that have been associated with atherosclerosis in human populations, including plasma lipid levels, insulin/glucose levels, blood cell levels, obesity and TMAO levels." (PMID 26694027, 2015). "We hypothesized that in the presence of genetic or obesity-induced concurrent insulin and leptin resistance, Kiss1 neurons would be unable to maintain reproductive function." (PMID 25946091, 2015). "Our findings suggest that, in addition to the central resistance to certain hormones regulating food intake, such as leptin or insulin, central resistance to glucagon-induced hypophagia might also contribute to the development of obesity." (PMID 26909312, 2015). "Furthermore, a number of animal studies where inflammatory pathways are genetically down regulated demonstrate that preventing obesity induced inflammation can prevent the development of insulin resistance." (PMID 26610527, 2015). "In addition, yerba maté inhibited hepatic Tnf-α and restored hepatic and muscle insulin signaling through an increase in IRS-1 tyrosine phosphorylation in mice with high fat diet-induced obesity." (PMID 25621503, 2015). "Our experiments in mice with diet-induced obesity demonstrated additive beneficial effects of a combined intervention using EPA + DHA and thiazolidinediones on insulin sensitivity, glucose tolerance, metabolic flexibility, lipid metabolism, hepatic steatosis, inflammation and obesity." (PMID 26633989, 2015). "Several studies in such models of obesity and diabetes have demonstrated an improved metabolic profile (including but not limited to reduced levels of glucose, insulin, HbA1c, LDL-cholesterol, triglyceride and leptin) following administration of different strains of lactobacilli and bifidobacteria." (PMID 25825594, 2015). "Moreover, insulin is able to increase myocardial blood flow also in conditions characterized by coronary dysfunction such as obesity, diabetes type 1, and coronary artery disease." (PMID 26124827, 2015). "There are three important peripheral signals that could participate in the altered GH secretion of obesity, leptin, insulin and ghrelin." (PMID 25782001, 2015). "Importantly, n-3 PUFA administration alleviates high-fat diet (HFD)/obesity-induced insulin resistance, which is equal to or greater than the effects of clinically used insulin sensitizing drug." (PMID 26339623, 2015). "Additionally, 3w SRD CBA, but not B6, mice had increased fat mass providing support for the observation that high insulin levels drive obesity under energy-rich conditions." (PMID 26085100, 2015). "FGF21 reverses hepatic steatosis, counteracts obesity, and improves insulin insensitivity." (PMID 26441837, 2015).
Obesity (continued). "Third, most study participants were in the midst of puberty, a period when hormonal status may influence the indices of obesity, as well as insulin sensitivity." (PMID 25970186, 2015). "This warrants investigation, since D3R may play a role in insulin secretion in the periphery, and D3R knockout mice have been characterized as having an obesity-prone phenotype." (PMID 25716779, 2015). "Collectively, the coexistence of obesity and T2D suggests that patients with these conditions have a fertile whole-body environment saturated in growth factor signals (insulin), an abundance of circulating nutrients (glucose, FAs), inflammatory cytokines, and reactive oxygen species." (PMID 25961014, 2015). "Therefore, advisably inhibiting PTP1B activity is considered to evoke multiple series of physiological responses to resist T2DM and obesity via facilitating tyrosine phosphorylation of insulin signaling molecules." (PMID 26064877, 2015). "Interestingly, studies with BMI or anthropometrics as primary outcome measures had lower retention rates than studies with other primary outcome measures (e.g., obesity-related behavior, insulin sensitivity; 82.9 % vs. 89.0 %)." (PMID 26651822, 2015). "To establish the validity of our mice models with metabolic syndrome and the efficacy of the six month HFD treatment, we assessed four vital parameters that are indicative of metabolic disorders: obesity, glucose intolerance, insulin insensitivity, and high blood cholesterol." (PMID 25950605, 2015). "Hence, the cross- talk between JNK signaling and insulin signaling in this HFD-induced obesity model seems to be center-stage of insulin resistance." (PMID 26023930, 2015). "Ksr 2−/− mice display obesity, high insulin levels, and impaired glucose tolerance." (PMID 25825681, 2015). "Taken together, these results suggest that chronic vglycin treatment ameliorates metabolic stress in middle-aged T2DM mice by improving glucose and insulin tolerance to control obesity and normalize plasma glucose, consistent with our previous findings in young T2DM Wistar rats." (PMID 26510947, 2015). "In obesity, adipokines secreted by adipocytes and macrophages also act in an autocrine fashion to further exacerbate adipose tissue inflammation, and decrease muscle and liver insulin sensitivity." (PMID 26110385, 2015). "Besides JNK peripheral role in obesity, studies provide evidences that JNK deficiency in the central nervous system, mostly of hypothalamic–pituitary axis, improves insulin sensitivity and reduces body mass." (PMID 26635627, 2015). "Obesity is characterized by a varying degree of resistance to the physiological effect of insulin." (PMID 24798033, 2015). "When provided normal nursing, intrauterine growth-restricted newborns demonstrate significantly increased food intake with rapid catch-up growth, which results in adult metabolic syndrome, including obesity, increased percentage body fat, lipid abnormalities, and insulin resistance." (PMID 25738800, 2015). "This would suggest that the relationship of ADHD to obesity can be explained, at least in part, by fetal programming hypothesis or the fetal insulin hypothesis." (PMID 24633695, 2015). "For example, Rag-/- and Scid mice, which lack both T and B cells, are more insulin-resistant than WT mice when fed a high-fat diet (HFD), suggesting that T and B cell responses may be protective in obesity-associated inflammation and insulin resistance." (PMID 26317499, 2015). "In vivo, TLR-3 deficiency did not significantly influence HFD-induced obesity, insulin sensitivity or inflammation." (PMID 25867514, 2015). "Although controversial, it has been also suggested that ZAG might inversely reflect the status of insulin sensitivity in obesity." (PMID 26068931, 2015). "Obesity, mainly visceral fat, contributes to insulin resistance." (PMID 25652009, 2015). "Furthermore, PI3Kγ inhibition is also related to ameliorate obesity complications, mostly improving systemic insulin sensitivity." (PMID 26635627, 2015).
Obesity (continued). "One hypothesized reason for impaired insulin signaling has been thought to be due to the chronic systemic low-grade inflammation in obesity." (PMID 26779183, 2015). "Adipokines play an important role in the regulation of appetite and satiety, inflammation, fat distribution, insulin sensitivity, and energy expenditure, among others, and are promising molecular candidates for the development of new treatments for obesity and its related diseases." (PMID 25918733, 2015). "The continued rise in global rates of obesity, which is typically accompanied by elevations in systemic insulin and IGF-I levels, suggests that efforts to develop pharmaceutical agents that reduce this signaling for cancer prevention and treatment are particularly warranted." (PMID 26029167, 2015). "Hence, we chose to study human primary adipocytes alone to avoid AT complexity and obtain a clear detailed picture of human adipocytes and its link with obesity and insulin regulation." (PMID 25743104, 2015). "Next, we tested our primary hypothesis that reduced insulin levels early in life might attenuate diet-induced obesity." (PMID 26155745, 2015). "However, almost all of these studies were carried out in adults with a high prevalence of obesity and type 2 diabetes, and very few studies have investigated the relationship between insulin and weight gain in early childhood." (PMID 26047327, 2015). "This unhealthy pattern of obesity was coupled with insulin resistance and low-grade inflammation." (PMID 25866590, 2015). "Interestingly, VAT Treg cells reduce strikingly and specifically in insulin-resistant models of obesity." (PMID 26339623, 2015). "In the current study, there were no changes typically associatedwith obesity in OR rats, since the high-fat diet was not able to promote changes inglucose, lipid, insulin, leptin, or blood pressure profiles." (PMID 26761369, 2015). "Since males typically exhibit significantly more robust metabolic deficits in response to high-fat diets, this may suggest that some aspects of obesity-induced cognitive impairment are related to metabolic disturbances, including insulin resistance." (PMID 26217222, 2015). "Interestingly, a short-term NPY overexpression study suggested that NPY influences leptin and insulin secretion independently from food intake and obesity." (PMID 25993471, 2015). "In fact, abdominal obesity can result in higher insulin concentration; and the resultant hyperinsulinaemia may encourage further obesity." (PMID 25995732, 2015). "A transient attenuation of insulin hypersecretion in young, growing Ins1−/−:Ins2+/− mice allowed us to test the secondary hypothesis that these anti-obesity effects would persist despite late-onset HFD-induced elevations in insulin." (PMID 26155745, 2015). "Although the clinical and experimental studies that link P-glycoprotein to obesity-associated drug resistance are absent, the connection between insulin and P-glycoprotein has been established." (PMID 26084465, 2015). "FGF21 transgenic animals show lower levels of serum insulin, glucose, triglycerides (TG), cholesterol, lower hepatic TG content, improved insulin sensitivity, resistance to diet-induced obesity, and a significantly extended lifespan compared with their wild-type counterparts." (PMID 26594197, 2015). "In addition, several studies suggested that T cell-derived IL-22 enhances IL-1β-mediated inflammation in human adipose tissue and reduces insulin sensitivity in human hepatocytes, promoting obesity and diabetes." (PMID 26064446, 2015). "Other than insulin-related deficits induced by obesity, increased adiposity has other systemic effects that may contribute to induction and progression of AD." (PMID 26217222, 2015). "Moreover, the overexpression of adiponectin in mice is sufficient to improve insulin sensitivity in high fat diet-induced obesity mice models." (PMID 25918733, 2015).